CD44 (CD44 molecule (IN blood group))
Diseases named in the same sentence as CD44 in open-access papers (continued):
Sharing a sentence is not in itself a finding about the gene and the disease.
tumor (continued). "Recent studies indicated CD44 was highly related to poor prognosis of HCC and responsible for tumor progression." (PMID 33661757, 2021). "Glycolysis is preferred in breast CD44+CD24lowEPCAM+ CSCs, sphere-forming radio-resistant nasopharyngeal carcinoma cells and CD133+CD49f+ tumor initiating cells (TICs) in hepatocellular carcinoma." (PMID 34804950, 2021). "CD44 interacts with various ECM components, proteins and cytokines present in the tumour microenvironment." (PMID 34944493, 2021). "Compared with normal kidney tissues, antibody stainings for ANKZF1, CD44, IDUA, KIF20A, PLOD2, and VCAN were high in ccRCC tumor tissues, whereas they were low for CHST6, HS6ST2, NDST3 and FBP1." (PMID 33836688, 2021). "Quantitative PCR was used to examine the effects on mRNA levels of platelet-derived growth factor (PDGFB), tumor vascular marker CD105, and cell adhesion molecules ITGA5, ITGB1, and CD44." (PMID 34176441, 2021). "mRNA levels of Ki-67, CD24, CD44, CD31, MENA, CD49, ECAD, PCAD, EpCAM, CDX2, CK6, CK7, CK13, were significantly decreased in tumour tissue relative to non-tumour tissue." (PMID 33906633, 2021). "This cell phenotype has been further refined whereby CD44+CD24-/low cells expressing active ALDH1, enriched following doxorubicin treatment, were able to reproduce the bulk tumour in a mouse xenograft model." (PMID 33799834, 2021). "Several studies have reported that CD44, and especially the CD44 splice isoform CD44s, positively correlates with EGFR tumor signatures and predicts poor survival in different types of cancers." (PMID 33981532, 2021). "Particularly, miR-34a has been confirmed to be a well-defined tumor suppressor which could persuade the cell apoptosis, the cell cycle arrest at G1 phase and also restrain the migration of tumor cells by decreasing the expression of Bc1-2, Notch-1, survivin, CD44 and the cyclin family." (PMID 34443415, 2021). "Subsequent qRT-PCR analysis also showed that the expression level of CD44, DPP4 and SLC7A11 in ccRCC samples are significantly higher than that in paired non-tumor samples." (PMID 34370716, 2021). "In tumor cells, PI3K/Akt signaling pathway is reported to involve cell proliferation and apoptosis via CD44/HA interaction." (PMID 34404442, 2021). "As reported, the CD44+CD24- subpopulation of PCa cells are stem-like cells that are responsible for colony and tumor initiation." (PMID 34242345, 2021). "The expression of stem cell markers such as ALDH1, BMI-1, CD44, Nanog, and SOX2 is well-investigated for other tumour entities, and has shown promising results as prognostic parameters with potential as a target for cancer treatment." (PMID 33009929, 2021). "The study found that MSI1 as a stem gene in colorectal cancer cells is a key regulator of CD44+ CSC development and enhances tumor stem cell therapy resistance by triggering the formation of anti-apoptotic stress granules (SGs)." (PMID 33588867, 2021). "Our results demonstrate that zinc phthalocyanine (ZnPc)-PDT with 12 J/cm2 or 24 J/cm2 irradiation can substantially decrease tumor migration via downregulating MMP9 and ROCK1 and inhibit the clonogenicity of SW480 cells via downregulating CD44 and SOX2." (PMID 34833970, 2021). "In order to study the specific effect of macrophages on tumor cells through the common L–R pairs (TNFSF12–TNFRSF12A and SPP1–CD44), we further calculated the correlation between the TNFRSF12A or CD44 expression and hallmark signature scores in cancer cells." (PMID 34676217, 2021). "We then revealed that CSC score (based on CD44, CD24, and ALDH1A1) was correlated with tumor progression and TB." (PMID 35083162, 2021). "mRNA levels of Ki67, CD24, CD44, CD31, MENA and ECAD were reduced in tumour tissue relative to normal tissue, whereas the protein expression was increased in the tumour compared to normal tissue." (PMID 33906633, 2021).
tumor (continued). "Other stem cell markers have been shown to be present in a higher amount in CRC budding areas, e.g., a statistically significant relationship was found between the CSC markers Notch1, CD44 and ALDH1 and tumour budding." (PMID 34884696, 2021). "Silencing XBP1 and CD44 reduced tumor cell invasion and adhesion to HBMECs, whereas silencing CXCR4 decreased the tumor cells migration." (PMID 34093792, 2021). "CD44 was proved to be a marker of BC progression and stem-cell properties, and CD34 can promote tumor vascular endothelial cell proliferation, tumor invasion, and metastasis." (PMID 37305162, 2021). "Compared with the unconverted CD44-/CD24- tumor cells, PPME1, RHBDL2 and HIST1H4H mRNA transcripts increased in the newly converted CD44+/CD24- CSCs with a change of >two folds, which were similar to that in parental CD44+/CD24- CSCs." (PMID 34318746, 2021). "High expression levels of PD-L1 are also observed in CD133+CD44+ colorectal CSCs and CSC-enriched tumor spheres." (PMID 34235155, 2021). "The cell surface glycoprotein CD44, as a marker of trastuzumab resistance, is highly expressed in the plasma membrane of JIMT-1 control tumor cells." (PMID 34775489, 2021). "Immune checkpoint molecules, such as CTLA4, NRP1, TNFSF15, CD44, and BTLA, are present in the TME or on the surface of tumor cells, and they negatively regulate T cell activation." (PMID 34926701, 2021). "This CD44-CAdTrio allowed HER2-CAR T cells to kill numerous CD44v6+ head and neck carcinoma cell lines and improve tumour control and survival." (PMID 34944493, 2021). "Like CD44, RHAMM undergoes alternative splicing as truncated isoforms were detected in tumor cells, and it has been reported to be highly expressed in several tumors, including breast, colon, brain, prostate, and endometrial." (PMID 34360868, 2021). "The protein expression of CD44, HK3, KIF20A, and IDUA was higher in the tumor tissues compared to the normal tissue, and the protein expression of GALM and TGFA was lower in tumor tissues than normal, which was consistent with our results in TCGA." (PMID 33816274, 2021). "Such myofibroblast-deleted tumours enhanced tumour hypoxia, EMT program and CD44+CD133+ CSC phenotype, while decreased angiogenesis and cytotoxic CD8+/Treg ratio." (PMID 33941245, 2021). "CD44, a cell-surface glycoprotein involved in cell–cell interactions, cell adhesion, and migration, can interact with MMP9 to promote tumor growth and metastasis." (PMID 34073849, 2021). "In contrast, fluorescent images of mice treated with MWNT-HA-ICG and MWNT-HA-ICG/DOX showed favorable accumulation at tumor sites, which was attributed to the EPR effect and CD44-guided tumor targetability." (PMID 34959425, 2021). "The microRNA-34a-loaded NPs evaluated in a mouse model of gastric tumor showed the inhibition of CSC migration and tumor formation, induced apoptosis, and eliminated the CSC subpopulation of tumor cells by suppressing the CD44 expression." (PMID 34361141, 2021). "In CP, high proliferative activity and high-level expression of CD44 and CAV1 suggest a more aggressive tumor behavior." (PMID 33672734, 2021). "Many stem cell markers, such as CD44 and CD133, have critical roles in the formation and development of tumours." (PMID 33314691, 2021). "Compared to MDA-MB-231 and RT-R-MDA-MB-231 cells, CD24−/low/CD44+ cells isolated from RT-R-MDA-MB-231 cells showed increased proliferation, migration and invasion abilities, and induced expression of tumor progression-related molecules." (PMID 34502547, 2021). "Mounting evidence has shown that CD44 is a crucial CSC marker and is critical in regulating cancer cell self-renewal, tumor initiation, and metastasis." (PMID 34949193, 2021). "MGO-induced carbonyl stress can also enhance the degree of malignancy of tumor cells and increased the expression of tumor proliferation and migration markers CD29, CD44, and Msi-1." (PMID 34947850, 2021).
tumor (continued). "Tumor budding cells express high levels of the cancer stem cell markers LGR5, ALDH1A, CD44, and always escape immune surveillance." (PMID 34771607, 2021). "Subsequently, we sought to examine the TICs marker CD44 and CD133 in 3D cultured tumor cells by flow cytometry and quantified real-time PCR." (PMID 34758833, 2021). "Most tumors, including OSCCs, are populated with specialized oncogenic cells positive for CSC markers such as CD44, PROM1, ABCG2, and ALDH-1 and demonstrate a superior capability to develop a tumor when transplanted into other animals." (PMID 34205649, 2021). "We and others described a surface staining pattern of CD44 in HNSCC cell lines and tissue samples, an observation that indicates its role as an adhesion molecule during tumor survival and progression." (PMID 34307351, 2021). "The identification of tumor-initiating cells (TICs) has traditionally relied on surface markers including CD133, CD44, CD117, and the aldehyde dehydrogenase (ALDH) enzyme, which have diverse expression across samples." (PMID 33445692, 2021). "CD44+/CD24−/CD133− cells form the most aggressive colon tumors, removing the requirement of CD133 in tumor onset." (PMID 33562604, 2021). "Our results showed that zotarolimus and zotarolimus combined with 5-FU greatly reduced the presence of CD44, EGFR, and TGF-β in tumor immunostaining." (PMID 34361836, 2021). "For example, CD44 12-14, CD133 15, and EpCAM 16 were often used as markers of traditional tumor stem cells." (PMID 34239355, 2021). "However, the reason for the observed increased tumorigenic potential of CD44+CD133+ tumor-initiating cells in primary xenografts is largely unknown and a mechanistic explanation for the enhanced tumorigenicity of the CD44+CD133+ subpopulation of primary xenografts remains enigmatic." (PMID 33994850, 2021). "Of note, the described microRNAs target not only EMT‐TFs themselves, but also genes like BMI1, CD44, CD133, JAG1, or MYC that are involved in tumor‐relevant “non‐classical” EMT functions like stemness and survival." (PMID 34459003, 2021). "Tumor stroma (fibronectin) in red, tumor cells (EpCAM in EGI-1, MMTV-PyMT, and KPC tumor models, CD44 in mPDAC tumor models), in blue and T cells (CD8 in mPDAC and KPC, Calcein in MMTV-PyMT, and EGI-1 tumor models) in green." (PMID 34106045, 2021). "Double‐labeling immunofluorescence demonstrated that CD44 and VEGF were co‐localized in the same tumor cells." (PMID 33543833, 2021). "In contrast, both tumours were equally infiltrated with CD4+ T cells, which included similar percentages of CD44+CD62Lneg cells." (PMID 34471106, 2021). "CD24/CD44 analysis showed coordinated downregulation of CD24 and upregulation of CD44 in CTCs in the BM18 and LuCaP105 PDX models in comparison with their tumours." (PMID 34206049, 2021). "In ChS studies, researchers also identified high expression of CD44 (phagocytic glycoprotein 1, PGP-1)—a tumor stem cell marker, but also a lymphocyte homing receptor and a receptor for hyaluronan, osteopontin (OPN), collagens, and MMPs." (PMID 33804155, 2021). "Previous study reported that ascites-derived tumor cells exhibit CSC properties and ALDH combined with CD44 were used as markers to characterize OCSC-like cells." (PMID 33726845, 2021). "In the ectopic tumour model receiving castration and bicalutamide therapy, massive solid tumours were observed in ALDH+CD44+CXCR4+CD24+-cell-injected mice, whereas the ALDH−CD44−CXCR4−CD24− cells yielded smaller tumours." (PMID 34247196, 2021). "Therefore, a better understanding of the alteration of HA homeostasis in the tumor microenvironment and the molecular mechanisms involved in controlling HA and CD44 during cancer progression may significantly contribute to increase the efficiency of anticancer therapies." (PMID 33981532, 2021).
tumor (continued). "Recently, it has been demonstrated that knockdown of Wnt1 decreases the expression of CD44, Aldehyde dehydrogenase 1 (ALDH1) and Sca-1 stemness genes, thus leading to the reduction of CSC subpopulation and tumor sphere formation in BC cells." (PMID 34354950, 2021). "Colorectal cancer CSCs have been independently identified as cells in the bulk tumour expressing the specific markers CD133 and CD44, by sphere formation, ALDH1 activity, and the presence of SPs." (PMID 33799834, 2021). "Mechanistically, HCQ and HCQ/AZ inhibited PD-L1 expression on tumor cells, while specifically targeting the anti-PD-1 induced increase in progenitor CD8+CD44+PD-1+TCF1+ tumor infiltrating T cells (TILs) and the generation of CD8+CD44+PD-1+ effectors." (PMID 34181666, 2021). "To address the role of NUMB in CD44+ PCSCs, we altered the expression of NUMB in the CD44+ and CD44− PC3 cells and then performed tumor invasion, clone formation and sphere formation assays." (PMID 34045601, 2021). "By comparing the gene expression profiles of orthotopic and subcutaneous PCa tumours, we selected five widely used CSC markers (ALDH, CD44, CXCR4, α2β1 and CD24) to sort candidate PCSCs from orthotopic PCa tumours." (PMID 34247196, 2021). "CD44 is a CD marker with functions such as cell adhesion, cell growth, epithelial-mesenchymal transition (EMT), and tumor progression." (PMID 34094034, 2021). "CSCs are identified as the population of tumor cells positive for the unique composition of CSCs markers (CD133, CD44, CD166, ALDH positivity, and others, depending on cancer type)." (PMID 33957885, 2021). "Reverse transcription-quantitative PCR assays revealed that RAMP2-AS1, CD44, CCND3, NCALD and MACF1 expression was lower in tumor tissues than in normal tissues, while miR-296-5p expression was higher in tumor tissues compared with in normal tissues." (PMID 33281971, 2021). "We examined CSC markers (CD133, CD44, and ALDH1) expression for tumor formation capacity and the potential effect of Calebin A on these CSC markers." (PMID 34660256, 2021). "During the EMT process, tumor cells also acquire progenitor/stem cells (CSC) marker expression (e.g., CD44, CD133, Nanog, and OCT-4) and properties, notably self-renewal, asymmetric cell division, tumor initiation, drug resistance, and disease recurrence." (PMID 33923958, 2021). "They discovered that the OPN/CD44 immune checkpoint controlled cytotoxic T lymphocytes (CD8+ T) cell activation and tumour immune evasion." (PMID 34944493, 2021). "Tumor-secreted OPN also binds to αVβ3 integrin and CD44 on fibroblasts to reprogram normal fibroblasts into tumor-promoting cancer-associated fibroblasts in mammary carcinoma." (PMID 33670921, 2021). "The NPs can accumulate in the tumor site through EPR effect, and can be endocytosed by tumor cells through HA binding to over-expressed CD44 on cancer cells surfaces." (PMID 34071794, 2021). "Circulating double positive CD44 and ALDH1/2 cells were shown to have an increased capacity for tumor initiation and are characteristic for cancer stem-like cells." (PMID 35008299, 2021). "On the other hand, tumor cells were evaluated for the expression of the surface markers CD133, CD44, and CD34." (PMID 37305162, 2021). "Alternative splicing of CD44 mRNA regulated by ESRP1 increases xCT-dependent resistance to redox stress, thereby allowing tumor cells to evade exogenous stress in the pre-metastatic niche." (PMID 33401672, 2021). "Other markers including Ki67, PCNA, DAXX, CD24, CD44, CD31, MENA, Laminin, ECAD, PCAD and CDX2 and CK14 showed different trends in expression between tumour and non-tumour with qRT-PCR compared to IHC." (PMID 33906633, 2021). "Finally, HPGD which encodes the PGE2 signal terminator 15-PGDH is significantly upregulated in the CD44+/CD24- tumor cells; this could negate any increased production of PGE2 cells due to increased PLA2/COX-2, since increased 15-PGDH would degrade produced PGE2." (PMID 35127497, 2021).
tumor (continued). "The phosphorylation of EGFR prompted by the interaction between HA and CD44 has been shown to regulate ERK 1 and ERK 2, key in driving tumor cell proliferation and migration." (PMID 34199373, 2021). "In larger vessels of tumor adjacent lung tissue as well as in normal/healthy lung tissue, CD34 clearly marks the vasculogenic zone, where also CD44‐positive LR‐MSCs reside, which coexpress the MSC marker CD146." (PMID 32830458, 2021). "FAT1 is frequently inactivated resulting in increased tumor stemness and metastasis in a mouse model of SCC involving CAMK2, CD44, and SRC activities that induce nuclear translocation of YAP1 and ZEB1." (PMID 34459003, 2021). "When 89Zr-anti-CD44 was administered to Balb/C nude mice, there was remarkably high splenic uptake but low SNU-C5 tumor uptake (1.2 ± 0.7%ID/g)." (PMID 33594192, 2021). "It was correlated with high-grade tumours and poor overall survival and involved in ALDH+CD44+CXCR4+CD24+-cell-rendered castration resistance." (PMID 34247196, 2021). "Here, we identified that high expression of CD44 enhances EMT and cancer stemness of irradiated GBM cells, leading to tumor aggressiveness." (PMID 34681583, 2021). "The CD44+/CD24− lineage cells generally possess a mesenchymal or myoepithelial-like phenotype and are found more peripherally at the tumor edge." (PMID 34944829, 2021). "The activation of Rho ATPase by CD44 enhances the cytoskeletal transformation and invasion, while other pathways like PI3K-AKT and MAPK-Ras enhances tumor cell growth, survival, and invasion." (PMID 35431911, 2021). "It has been found that EMT tumor cells have the ability for self-renewal, unlimited proliferation and anti-apoptosis, and highly express CD133, CD44 + and ABCG2." (PMID 33992097, 2021). "RHAMM and CD44 play a role in cell adhesion to the extracellular matrix (ECM) and are required for tumor cell invasion and metastasis." (PMID 33406809, 2021). "When 89Zr-anti-CD44 was injected with a total Ab dose of 700 μg, PET images showed further reduced spleen uptake and further increase of HT29 tumor uptake." (PMID 33594192, 2021). "Accumulating evidence indicates that CD44 isoforms, especially CD44v isoforms, are CSC markers and critical players in regulating the properties of CSCs, including self-renewal, tumour initiation, metastasis and chemoresistance." (PMID 35006432, 2021). "CD44 is a cell-surface receptor for OPN and mediates epithelial-mesenchymal transition; hence, it is related to tumor migration." (PMID 34722241, 2021). "To determine the effect of Tocilizumab in CSCs vs. bulk tumor cells, we sorted cells for ALDH/CD44 and performed western blot analyses." (PMID 34689150, 2021). "Accumulating evidence shows that CD44, especially its CD44v isoforms, are CSC markers that play critical roles in regulating the properties of CSCs, including self-renewal, tumor initiation, metastasis, and chemo/radio resistance." (PMID 34349642, 2021). "Recent studies showed that in colon tumorigenesis, HA interacts with both CD44 and the abundant TLR4, promoting the growth of tumor grafts in mice." (PMID 34360868, 2021). "The relative fold of CD44+TMCC3+ subsets in metastatic lymph node was 2.72 ± 0.7, as compared with primary tumor cells (n = 5, p = 0.04)." (PMID 33742122, 2021). "GSCs (both SU4 and SU5) had a strong ability to form tumor-sphere like cell clusters, and expressed GSCs markers, including CD133, nestin and CD44, consistent with the GSCs stemness characteristics." (PMID 33621205, 2021). "TAMs preferentially secrete TGF-β to stimulate CSC-like properties by inducing EMT, while TAM-derived IL-6 induces CD44+ HCC stem cell expansion by activating STAT3, thus promoting tumor development through CSC growth." (PMID 34235155, 2021). "Tumor cells express adhesion molecules, such as P-selectin glycoprotein ligand-1 (PSGL-1) and CD44, which bind to P-selectin on activated platelets to form aggregates." (PMID 34207884, 2021).